DSCAML1 (DS cell adhesion molecule like 1)
Description:
Cell adhesion molecule that plays a role in neuronal self-avoidance. Promotes repulsion between specific neuronal processes of either the same cell or the same subtype of cells. Promotes both isoneuronal self-avoidance for creating an orderly neurite arborization in retinal rod bipolar cells and heteroneuronal self-avoidance to maintain mosaic spacing between AII amacrine cells (By similarity). Adhesion molecule that promotes lamina-specific synaptic connections in the retina: expressed in specific subsets of interneurons and retinal ganglion cells (RGCs) and promotes synaptic connectivity via homophilic interactions (By similarity).
Synonyms: DSCAM2; KIAA1132
Tractability: Antibody: UniProt places it where antibodies can reach, with high confidence; its Gene Ontology location is reachable by antibodies, with high confidence; UniProt predicts a signal peptide or a membrane-spanning region. PROTAC: its protein half-life has been measured.
Gene: Protein-coding gene on chromosome 11 (117,427,772 to 117,817,525, reverse strand). Ensembl gene ENSG00000177103.
Subcellular location: Cell membrane; Synapse
Pathways (Reactome):
Developmental Biology: DSCAM interactions
Gene Ontology:
Molecular function: protein binding; protein homodimerization activity; cell-cell adhesion mediator activity
Biological process: brain development; embryonic skeletal system morphogenesis; homophilic cell-cell adhesion; axon guidance; axonogenesis; cell fate determination; central nervous system development; dendrite self-avoidance; dorsal/ventral pattern formation; nervous system development
Cellular component: cell surface; extracellular region; plasma membrane; axon; synapse
Genetic constraint (gnomAD): Loss-of-function variants: 38 observed, 196.94 expected, observed/expected ratio (o/e) 0.19, 90% interval 0.15 to 0.25. The upper end of that interval is the gene's LOEUF score, 0.25, which puts it in group 1 of 6, group 1 being the genes least tolerant of losing a copy. Missense variants: 2,197 observed, 2,871.1 expected, observed/expected ratio (o/e) 0.77, 90% interval 0.74 to 0.79. Synonymous variants: 1,202 observed, 1,169.6 expected, observed/expected ratio (o/e) 1.03, 90% interval 0.98 to 1.08.
Homologues: Orthologues: chimpanzee DSCAML1 (99% identical), macaque DSCAML1 (99% identical), dog DSCAML1 (99% identical), pig DSCAML1 (99% identical), rabbit DSCAML1 (98% identical), mouse Dscaml1 (98% identical), rat Dscaml1 (98% identical), guinea pig DSCAML1 (96% identical), tropical clawed frog dscaml1 (86% identical), zebrafish dscaml1 (64% identical). Paralogues in human: DSCAM (60% identical), MXRA5 (17% identical), HMCN2 (16% identical), IGSF10 (16% identical), SDK2 (12% identical), SDK1 (11% identical), NEO1 (11% identical), DCC (10% identical), ROBO3 (10% identical), ROBO1 (10% identical), ROBO2 (9% identical), NRCAM (9% identical), and 24 more.
Diseases named in the same sentence as DSCAML1 in open-access papers:
DSCAML1 is named in the same sentence as 21 diseases in open-access papers, as found by Europe PMC text mining. Sharing a sentence is not in itself a finding about the gene and the disease. The quoted sentences say what the papers report.
Down syndrome (4 papers, 2015 to 2022). "MKRN3 is associated with Prader Willy Syndrome, NPAP1 both with Prader Willy Syndrome and Angelman Syndrome while DSCAML1 with Down Syndrome." (PMID 28993790, 2017). "Down Syndrome (DS) Cell Adhesion Molecules (DSCAMs) represent a small group of transmembrane proteins of the immunoglobulin superfamily comprising, in vertebrates, DSCAM and its paralogue DSCAM-like 1 (DSCAML1)." (PMID 33585465, 2020).
epilepsy (3 papers, 2020 to 2024). A brain disorder characterized by episodes of abnormally increased neuronal discharge resulting in transient episodes of sensory or motor neurological dysfunction, or psychic dysfunction. "Recently, the relationship of heterozygous variants in the DSCAML1 gene with epilepsy and neurodevelopmental disorders (NND) has been studied." (PMID 39156017, 2024). "In humans, rare variants in DSCAML1 are associated with several neurodevelopmental disorders, including autism spectrum disorder, cortical abnormality, and epilepsy." (PMID 36875755, 2023). "Since we identified Dscaml1 as a novel seizure-related gene in rats, we searched for DSCAML1 mutations in patients with epilepsy." (PMID 33256836, 2020). "Furthermore, we identified a single nucleotide substitution in a human epilepsy that would result in one amino acid change in DSCAML1 (A2105T mutation)." (PMID 33256836, 2020). "We found an A2105T-type mutation for DSCAML1 in an epilepsy patient." (PMID 33256836, 2020). "We performed Sanger sequencing of exons and adjacent sequences of the DSCAML1 gene in blood samples from the “Depository of the patients with epilepsy and intellectual disability” of our institute under informed consent guidelines." (PMID 33256836, 2020). "Genetic perturbations of DSCAML1 are seen in patients suffering from a wide range of mental health disorders, including intellectual disability, autism spectrum disorder, schizophrenia, epilepsy, and stress disorder." (PMID 36875755, 2023). "Furthermore, we performed genomic sequencing for the DSCAML1 gene in epilepsy patients with accompanying intellectual disabilities, and identified one nucleotide replacement that results in a one amino acid change from alanine to threonine at the 2105th residue of DSCAML1 (DSCAML1A2105T)." (PMID 33256836, 2020). "Although we identified Dscaml1 as the responsible gene for IER, this gene has not been shown to be a causative gene for human epilepsy." (PMID 33256836, 2020).
cervical cancer (1 paper, 2025). A primary or metastatic malignant neoplasm involving the cervix. "Comparing the mutation profiles of PMMC, the TCGA cohort (skin melanoma and cervical cancer), and the COSMIC cohort (skin melanoma), we found that DSCAML1 is the commonly mutated gene in both CC and PMMC." (PMID 41479783, 2025).
congenital stationary night blindness (1 paper, 2023). "A mutation in Dscaml1 has been linked to middle age onset of congenital stationary night blindness." (PMID 37910517, 2023).
leukemia (1 paper, 2022). A malignant (clonal) hematologic disorder, involving hematopoietic stem cells and characterized by the presence of primitive or atypical myeloid or lymphoid cells in the bone marrow and the blood. "We identified 147 CRGs from 153 leukemia samples with only five observed in more than one sample (CEP164, DSCAML1, FXYD2, SIK3, and GRIA4)." (PMID 35945623, 2022).
tumor (5 papers, 2014 to 2026). "TCF7L1, TEX13B, and DSCAML1 mutations, which were detected during exome sequencing, were not confirmed in subsequent Sanger sequencing of the primary tumor or any metastatic specimens." (PMID 24406431, 2014). "In this study, we identified tumor‐associated axonogenesis as the key determinant of PNI in KRASG12D PDAC and demonstrated that axonogenesis is driven by the transcriptional activation of DSCAML1 in neurons, which is regulated by EV‐packaged circPNIT from KRASG12D." (PMID 39488792, 2024). "While global methylation changes do not consistently predict transcriptional output, locus-specific effects, notably in DSCAML1, BAIAP2L1, and SHANK1, suggest potential mechanistic relevance and potential functional impact on tumor biology." (PMID 41597272, 2026).
neurodevelopmental disorder (3 papers, 2019 to 2024). A behavioral and cognitive disorder with onset during the developmental period that involves impaired or aberrant development of intellectual, motor, or social functions. "Given that several Dscam- and Dscaml1-linked neurodevelopmental disorders are associated to chromosomal region duplication events, we furthermore sought to examine the neurodevelopmental effects of Dscam and Dscaml1 gain of function (GOF)." (PMID 33585465, 2020). "Human DSCAML1 mutations are believed to be causative for neurodevelopmental disorders." (PMID 32038180, 2019).
cancer (2 papers, 2022 to 2026). A tumor composed of atypical neoplastic, often pleomorphic cells that invade other tissues. "Among differentially methylated genes, DSCAML1 exhibited higher expression in Cluster II tumors (not statistically significant), whereas BAIAP2L1 showed significantly lower expression in malignant tumors, consistent with locus-specific hypermethylation discussed previously." (PMID 41597272, 2026).
DSCAML1 also shares sentences with these, for which no sentence is quoted: intellectual disabilities (2 papers); Alzheimer disease (1); amyloid (1); Angelman syndrome (1); autism spectrum disorder (1); blinding (1); cognitive decline (1); Cornelia de Lange syndrome (1); ovarian epithelial cancer (1); Prader Willy Syndrome (1); schizophrenia (1); skin melanoma (1); type 2 diabetes (1).